CD44 (CD44 molecule (IN blood group))
Diseases named in the same sentence as CD44 in open-access papers (continued):
Sharing a sentence is not in itself a finding about the gene and the disease.
breast carcinoma (continued). "Different lines of evidence indicate that breast cancer stem cells (BCSCs) display increased cell motility, invasion, and overexpress genes that promote metastasis and can be traced by CD44+/CD24−/low surface marker expression." (PMID 25401416, 2014). "In breast cancer, the SNPs of CD44 are suggested to affect breast cancer development and prognosis by increasing CD44 expression." (PMID 24699672, 2014). "For example, CD44+CD24−/low population is tumorigenic with stem cell properties in breast cancer, but CD24+ cells were dramatically enriched in distant metastases in breast cancer patients." (PMID 25237769, 2014). "Given this, we first assessed LSR and CD44 expression in a panel of well-characterized breast cancer cell lines." (PMID 24990559, 2014). "Shipitsin and colleagues performed copy number analysis using DNA microarrays of CD44+ versus CD24+ cell populations from a single breast cancer patient and showed that both populations shared copy number alterations, indicating a clonal origin." (PMID 24998755, 2014). "The CD44+/CD24lo definition has also been found to enrich for cancer stem cells in the Her2/Neu mammary tumor mouse model." (PMID 25080108, 2014). "The most widely accepted markers to identify mammary cancer stem cells are the expression of CD44/CD24 and ALDH." (PMID 24498388, 2014). "Since CD44+CD24- breast cancer cells have been suggested to be cancer stem-like cells which also express the stem cell marker Sca1, we sought to determine the stemness capacity of the sorted cells." (PMID 24324806, 2013). "CD44 overexpression correlates with invasive and metastatic phenotype in breast cancer, and thus, is an indicator of poor prognosis." (PMID 23326564, 2013). "As biomarkers, CD44+/CD24-/low breast cells have been shown to have tumor-initiating properties in breast cancer, show enhanced invasive properties, and are more likely to become resistant to radiation therapy." (PMID 24167614, 2013). "Leukemia stem cells have been isolated from acute leukemic cells, and the first CSC/CIC population was isolated from breast carcinoma with the combination of CD44 and CD24 expression." (PMID 23967051, 2013). "Further, activated Jak-STAT signalling is essential for the survival of CD44+/CD24-/low stem-like breast cancer cells and was shown to play an important role during mammosphere formation." (PMID 24229464, 2013). "Several studies in breast cancer have demonstrated that EMT induced an increase in the CSCs population defined as CD44+CD24−." (PMID 23484135, 2013). "BCSCs from a breast cancer patient with a CD44+/CD24− phenotype were isolated and maintained using mammosphere culture media." (PMID 23301003, 2013). "The CD44+CD24neg/low breast cancer population was shown to be enriched for cancer initiating stem cells." (PMID 23982961, 2013). "The relation between β-catenin and CD44 has been studied in many solid tumors such as breast cancer, prostate cancer and colon carcinoma." (PMID 24257075, 2013). "ALDH1+CD44+CD24neg subpopulations in breast cancer lines yielded more xenograft metastasis than ALDH1-CD44low/−CD24+, but metastatic potential was not limited to the very low minority ALDH1+ population." (PMID 23982961, 2013). "Breast cancer stem cells can be identified by a CD44(+) CD24(-/low) phenotype that augments mammosphere formation in vitro and exhibit increased resistance to chemo- and radiotherapy." (PMID 24392029, 2013). "A CSC gene signature from comparative analysis of CD44+CD24− sorted tumor cells and cancer mammospheres showed that this signature was associated with claudin-low breast cancers, suggesting that claudin-low tumors are enriched for CSCs." (PMID 23986719, 2013). "When we co-cultured breast cancer cells with MSCs, we observed a marked expansion of the CD44+/CD24-/lo CSC population, and a switch from asymmetric to symmetric segregation of template DNA." (PMID 24238140, 2013).
breast carcinoma (continued). "In breast cancer patients, administration of chemotherapy or radiation therapy increases the fraction of CD44+/CD24− tumor cells and augments mammosphere formation in vitro and tumorigenicity in xenotransplantation models." (PMID 23301003, 2013). "Recent experimental evidence suggests ALDH-positive (ALDH+), or cell surface molecule CD44-positive (CD44+) but CD24-negative (CD24−) breast cancer cells have cancer stem cell properties." (PMID 24376586, 2013). "We have illustrated here that STAT3 phosphorylation up-regulated hTERT then, activated hTERT enhanced cancer stem cell marker CD44 expression in breast cancer." (PMID 24386318, 2013). "In summary, this study demonstrates that STAT3 is activated in ALDH+ and ALDH+/CD44+/CD24− breast cancer cells." (PMID 24376586, 2013). "Cells isolated from human breast cancers marked by CD44+CD24−/low lineage are anoikis-resistant and capable of self-renewal as mammosphere (MS) colonies providing a link between MS and cell surface markers that enrich for tumorgenic cells." (PMID 23861811, 2013). "In vitro findings suggest that breast cancer cells with lymphatic metastatic ability and expressing the CD44+/CD24- immunophenotype have clonogenic potential and a higher ability to survive and grow in unfavorable environments." (PMID 23419168, 2013). "Controversial reports on the association of a CD44(+) CD24(-/low) phenotype and poor prognosis of breast cancer have been reported." (PMID 24392029, 2013). "The breast cancer stem cell signature was generated by combining two subpopulations of 36 breast tumors sorted for CD44+/CD24-/low markers and the cells that were able to form mammospheres on low-attachment plates." (PMID 24008095, 2013). "Breast cancers, for instance, are classified into several subtypes, such as luminal, basal, and HER2+, but the well-known CD44+CD24− phenotype is closely associated with the basal type, and the HER2+-type CSCs show an ALDH+ phenotype." (PMID 23626764, 2013). "To test this, we first knocked-down CD44 gene from the high CD44 (+) breast cancer cell line MDA-MB-231." (PMID 24386318, 2013). "Disulfiram, a drug used to manage alcoholism, has also been described as being able to kill CD44+ cells in models of breast cancer." (PMID 23593654, 2013). "It has been observed that BCSCs displayed higher incidence of human bone metastasis relative to the parental breast cancer cell line, and metastatic bone tissues strongly stained for CD44, CXCR4 and osteopontin." (PMID 23301832, 2013). "In primary breast cancers, CD44+CD24neg/low ESA+ cells were enriched for xenograft formation compared to bulk tumour cells." (PMID 23982961, 2013). "As few as 20 ALDH1+/CD44+/CD24−/low cells from breast cancer have been shown to initiate tumour growth; however such a small subpopulation capable of tumour growth is yet to be investigated in HNSCC." (PMID 23533441, 2013). "Because BLCs are a particularly aggressive and drug-resistant subset of breast carcinomas, targeting the Rb-low subsets with anti-CD44 therapy can potentially overcome the drug resistance." (PMID 24324613, 2013). "Interaction of CD44 with hyaluronan is involved in the regulation of breast cancer through cell-cell adhesion and inhibited invasion." (PMID 23940692, 2013). "Then in 2003, the first solid tumour CSCs were isolated from breast cancer using a CD44+CD24−Lin− marker phenotype." (PMID 23533441, 2013). "ALDH1 activity is very infrequent in CD44+CD24neg/low breast cancer cells, and populations enriched for both aldefluor activity and CD44+CD24neg/low show a high T-ISC frequency." (PMID 23982961, 2013). "We assessed the association between CD44+CD49f+CD133/2+ staining in normal adjacent tissue and breast cancer receptor subtype (defined by the expression of the estrogen (ER), progesterone (PR), or human epidermal growth factor-2 (Her2) receptors)." (PMID 24008095, 2013).
breast carcinoma (continued). "To test these scenarios, we co-cultured 3 breast cancer cell lines with human MSCs and analyzed expression of CD44 and CD24." (PMID 24238140, 2013). "In breast cancer cell lines and patient samples, CD44+/CD24−/ESA+-sorted TICs express higher levels of activated N4ICD than their non-TIC counterparts." (PMID 23593654, 2013). "The CD44+CD24neg/low primary human breast cancer population is enriched by taxane chemotherapy, and exhibits distinct gene expression profiles, prognostic of poor patient outcomes." (PMID 23982961, 2013). "Recent study showed that IL-6 had the ability to induce CD44 positive cancer stem cells in breast cancer oncogenesis model." (PMID 23593346, 2013). "Recently, CD44 has been recognized as one of the key cell surface markers for tumor-initiating cells in breast cancer." (PMID 23326564, 2013). "We examined STAT3 activation in ALDH+ and ALDH+/CD44+/CD24− subpopulations of breast cancer cells by sorting with flow cytometer." (PMID 24376586, 2013). "We quantified the frequency of asymmetric segregation of template DNA strands in 12 human breast cancer cell lines, and correlated the frequency to molecular subtype, CD44+/CD24-/lo phenotype, and invasion/migration ability." (PMID 24238140, 2013). "Using cell surface markers Al-Hajj and colleagues found that CD44+CD24−/low Lin− cells from breast cancer patients were significantly enriched for tumor forming ability in NOD/SCID mice compared with CD44+CD24+ Lin− cells." (PMID 23986719, 2013). "In a study comprising 30 metastatic breast cancer patients, it was shown that 80% of the patients had the CK+/CD44+/CD24−/low phenotype among their CTC and the mean prevalence per patient was 35.3%." (PMID 24305653, 2013). "CD24high expression in normal human mammary gland and breast carcinoma corresponds to a differentiated gene expression signature, whereas, CD44+ cells exhibit a more “stem-like” signature of gene expression." (PMID 23986719, 2013). "Several stemness markers have been described for the various histological subtypes of breast cancer, among them CD44, CD24, CD133, EpCAM, CD166, Lgr5, CD47, ALDH1 and the most recent ABCG2." (PMID 23976904, 2013). "NOTCH3 was also found to be upregulated in CD44+ populations of normal cells and breast cancer cells." (PMID 24355041, 2013). "Multiple studies have demonstrated a physical interaction between CD44 and Spp1 in a wide variety of cell types, including breast cancer cells, which alters an array of cellular phenotypes including motility and invasiveness." (PMID 24304664, 2013). "Earlier work showed primary human CD44+CD24neg/lowESA+ breast cancer cells were enriched for T-ISC, with <1/200 generating tumours in immune compromised hosts." (PMID 23982961, 2013). "CD24 is the most widely used marker, together with CD44, for identifying tumor-initiating cells in breast carcinomas." (PMID 23671674, 2013). "Accumulating evidence indicates that HIF-1α is significantly correlated with the rate of CSCs that express CD44+CD24−/low in the early stage of breast cancer." (PMID 23314174, 2013). "We further tested LLL12 against ALDH+/CD44+/CD24− breast cancer stem-like cells isolated from SUM159 cancer cells in a NOD/SCID mouse xenograft model." (PMID 24376586, 2013). "Various cancer-related cell-surface proteins are known to be transported into the nucleus in several cancers, including ErbB2 (breast cancer), CD40 (lymphoma), and CD44 (breast cancer)." (PMID 23638030, 2013). "We demonstrate that the ALDH+ and ALDH+/CD44+/CD24− subpopulations of breast cancer cells expresses higher levels of phosphorylated STAT3 (Tyrosine 705) (P-STAT3, Y705) than cell populations that do not express these stem cell markers." (PMID 24376586, 2013).
breast carcinoma (continued). "They found that the IL-6/JAK2/Stat3 pathway was preferentially active in CD44+ CD24− breast cancer cells compared to other tumor cell types." (PMID 23401782, 2013). "Cell surface biomarker CD44 plays an important role in breast cancer cell growth, differentiation, invasion, angiogenesis and tumour metastasis." (PMID 23940692, 2013). "Breast cancer cells that express the cell surface molecule CD44 (CD44+) but lack or have low expression of CD24 (CD24−) have been shown to have cancer stem cell properties." (PMID 24376586, 2013). "CD44+/CD24−/low breast cancer cells have the ability to metastasize, since the enrichment of these stem-like cells is significantly observed in patients with positive lymph nodes." (PMID 23671674, 2013). "This is a very interesting data, since the acquisition of increased expression of CD44 by noninvasive breast cancer cells correlates with the induction of EMT necessary for metastatic potential." (PMID 23762838, 2013). "Here we demonstrate that STAT3 physically interacts with CD44 and NF-kB and activates the catalytic subunit of telomerase (hTERT) in human breast cancer stem cells." (PMID 24386318, 2013). "In human cases, however, Giatromanolaki and colleagues found that breast cancer patients that present with CD44-/CD24- cells had a worsened overall survival." (PMID 23419168, 2013). "Stem-like cells with tumour initiating capabilities have been found to be enriched in the CD44+/CD24-/low sub-population of basal breast carcinoma cells." (PMID 24229464, 2013). "The relation between CD44 and neoplasms presents the breast cancer as the most well studied neoplasm; an experimental assay demonstrates that tumors within CD44-positive cell population possess cancer stem-cell behavior." (PMID 23419168, 2013). "Our data suggest that STAT3 is the linking molecule that connects CD44 and NF-kB signaling in aggressive breast cancer cell lines." (PMID 24386318, 2013). "IFN-γ production was found to be significantly reduced in the CD4+CD44+ T cell compartment in Il27ra−/− compared to Il27ra+/+ mice in both the fibrosarcoma and mammary carcinoma models." (PMID 23554861, 2013). "Recent studies also revealed CD44 overexpression potentiates the migration and invasion of breast cancer cells and promotes metastasis to the liver through CD44–HA / NFκB / cortactin signaling pathway." (PMID 23855374, 2013). "In breast cancer, CSCs have been identified as CD44+CD24-/low or aldehyde dehydrogenase positive (ALDH+)." (PMID 23883436, 2013). "In line with this, Krishnamachary and collaborators have reported that hypoxic regions of breast cancer specimens contain cells with elevated expression of CD44." (PMID 24285959, 2013). "It has been well established that breast cancer stem cells are characterized by CD44+CD24- phenotype, expression of Sca1 with high rates of tumorigenicity, in vivo." (PMID 24324806, 2013). "This is consistent with a recent report showing that the CD44+CD24- phenotype contributes to breast cancer relapse." (PMID 24324806, 2013). "A recent study also showed significant increase in the CD44 expression in breast cancer when compared to normal breast epithelium." (PMID 23940692, 2013). "In metastatic breast cancer cells, Klf-4 expression increased the proportions of CD44+CD24low and mammosphere-forming cells." (PMID 23986719, 2013). "CD44 expression in human breast cancer cells enhances self-renewal, mammosphere growth as well as drug resistance." (PMID 23341935, 2013). "In fact, expression of various CD44 protein variants correlates with aggressive human cancers, including HNSCC and breast cancer." (PMID 24403253, 2013). "We demonstrate that the cell adhesion molecule CD44 (isoform 10) is exclusively present on the breast cancer-derived MPs relative to the leukaemic cell-derived MPs." (PMID 23593486, 2013).
breast carcinoma (continued). "CD44 has a well-established role in breast cancer invasion/metastasis and angiogenesis and is subject to extensive splicing and post-translational modification." (PMID 23457460, 2013). "Recent evidence suggests that two important molecular characteristics of BLCs are decreased expression of Rb tumor suppressor, and elevated expression of CD44, a marker of breast cancer stem cells." (PMID 24324613, 2013). "Recent studies have shown CD44 and its interaction with hyaluronan regulate breast cancer cell proliferation, migration and invasion." (PMID 23940692, 2013). "The subpopulation of breast cancer cells with CD44+/CD24− has been shown to exhibit enhanced invasive phenotype as an early step to metastasis." (PMID 23401782, 2013). "In breast carcinomas, CD44 has been identified as a key cell-surface marker for various cancer stem cells." (PMID 23341935, 2013). "Our data on STAT3 activation are consistent with previous studies on the preferential activation of STAT3 in CD44 positive breast cancer stem cells." (PMID 24386318, 2013). "CD44 is preferentially expressed in benign canine mammary tumors and normal mammary tissue versus simple carcinomas and metastatic cells." (PMID 23426189, 2013). "In human breast cancer, the CD44+/ESA+/CD24−/low cells have been tested as BCSCs, since they are able to differentiate into cells with diverse phenotypes, and have tumorous pluripotency to generate mammary tumors and metastases in vivo." (PMID 25401049, 2013). "Another study using flow cytometry showed that 6.1% of the lymph node metastases contained CD44+/CD24- cells and found an association between metastatic dissemination and increased numbers of cells with this phenotype in human mammary neoplasms." (PMID 24119896, 2013). "In another study using mammospheres, CSCs in canine mammary neoplasms exhibited a CD44+/CD24- phenotype in four different tumoral cell lines." (PMID 24119896, 2013). "The purpose of this study was to establish the relation of CD44 to BL-BCa and to characterize how HA/CD44 signaling promotes a protease-dependent invasion of breast cancer (BrCa) cells." (PMID 22621373, 2012). "In a review of previous studies, Clarke proposed that ER–, PR–, and CD44+ CD24–/low cells in breast cancer have the same characteristic of tumorigenic breast cancer stem cells." (PMID 23554768, 2012). "PLK1 was universally expressed in breast cancer cell lines, representing all of the breast cancer subtypes, and was positively correlated to CD44." (PMID 22309939, 2012). "One of the widely accepted markers of breast cancer stem cells (BCSCs) is the cell surface marker CD44." (PMID 23226410, 2012). "Breast cancer cells with the CD44+/CD24− phenotype have been reported to be tumourigenic due to their enhanced capacity for cancer development and their self-renewal potential." (PMID 23028444, 2012). "Our data thus support an emerging role for CD44 as an important determinant of breast cancer progression, particularly in the setting of endocrine resistance." (PMID 23039365, 2012). "Further evidence for a relationship between “stemness” and Wnt signaling is provided by the recently reported association between nuclear/cytoplasmic ß-catenin and the putative stem cell surface marker phenotype CD44+/CD24− in human breast carcinomas." (PMID 22457761, 2012). "Herein, we provide evidence that IL-6 is capable of generating CD44+ cells with stem-like properties through induction of the EMT in the epithelial-like T47D breast cancer cells." (PMID 22134360, 2012). "In breast cancer, the up-regulation of CD44, a cell surface glycoprotein involved in cell-cell and cell-extracellular matrix adhesion, migration, differentiation and survival, is associated with cancer stem cells." (PMID 23226410, 2012).